CCL2 (C-C motif chemokine ligand 2)
Diseases named in the same sentence as CCL2 in open-access papers (continued):
Sharing a sentence is not in itself a finding about the gene and the disease.
COVID-19 (continued). "The increased presence of chemokines CCL2, CCL4, CXCL8, and CXCL10 in the plasma was observed among the Wuhan, Alpha, Delta, and Omicron variants of moderate to severe COVID-19 patients when compared to healthy individuals." (PMID 37632046, 2023). "It was reported that COVID-19 patients exhibited high plasma levels of C-C motif chemokine ligand 2 (CCL2), CXCL10, IFN-γ, IL-1β, IL-7, IL-8, IL-10 and TNF-α." (PMID 37251383, 2023). "Severe cases of COVID-19 are associated with prolonged, heightened levels of cytokines, such as IL-6, IL-8/CXCL8, CXCL9, CXCL10, TNF-α, MCP1/CCL2, RANTES/CCL5, IL-18, and MIP-1α/CCL3, which can last for up to two months." (PMID 36983995, 2023). "KC and CCL-2 serve as significant chemokines that attract neutrophils and monocytes to infection sites, thereby playing a pivotal role in the pathophysiology of COVID-19 and sepsis-induced lung injury." (PMID 37822934, 2023). "For instance, analysis of transcriptomic data in bronchoalveolar lavage of a patient with COVID-19 found high expression of CCL2, CCL3, CCL4, and CXCL10 when compared to healthy donors." (PMID 37632046, 2023). "Elsewhere, lung macrophages induced by MCP-1/CCL2 in patients with COVID-19 and lung involvement have been shown to share a transcriptional phenotype with macrophages stimulated by TNF alpha and IFN gamma." (PMID 37047772, 2023). "The transcription factor NF-κB is activated during viral infections, including COVID-19, and while upregulated it stimulates the production of chemokines such as monocyte CCL2 and CXCL10, which were also significantly upregulated in our study." (PMID 37832397, 2023). "Monocyte/macrophages in COVID-19 bronchoalveolar fluid from patients with severe COVID-19 were shown to express CCL2 and CCL7." (PMID 37892134, 2023). "This review describes the role of the CCL2/CCR2 and CCL5/CCR5 chemokine pathways associated with amplification of inflammatory responses in COVID-19 and the role of CVC in inhibiting this pathway." (PMID 35749425, 2022). "There was a marked upregulation of CCL2 and IL-6 expression in both severe and moderate COVID-19 groups (P<0.001), with thousands-fold difference compared with controls." (PMID 35982898, 2022). "Monocytes and macrophages accumulate in lung of severe COVID-19 patients, exhibit hyperinflammatory signatures, produce chemokines, such as CCL2 and CCL3; their frequency is correlated with older age and mortality." (PMID 35710943, 2022). "In the primary DILI sub-network of cluster 1, IL6, IL1B, TNF, and CCL2 were among the top ten key targets and related to the COVID-19 adverse outcome pathwaya inflammation of CRS exacerbated DILI." (PMID 35979235, 2022). "Many investigations have reported high levels of pro-inflammatory cytokines and chemokines, including IL-2, IL-6, IL-10, IFN-γ, CXCL10, and CCL2 in COVID-19." (PMID 35664675, 2022). "CXCL8 expression was significantly lower on days 1, 7, and 14, and the concurrent CCL2 expression was significantly lower on days 1 and 7 in patients with more severe courses of COVID-19." (PMID 36232655, 2022). "In this regard, it has been discussed that high production of some chemokines, such as CXCL8/IL-8, CCL-2/MCP-1, CCL3, CCL5, CXCL9, and CXCL10 are associated with lung damage and COVID-19 severity." (PMID 36685603, 2022). "As an indication of disease severity, we measured the mRNA expression levels of IFN-stimulated genes (IFIT1, IFIT3, ISG15, and MX2), pro-inflammatory cytokines (IL6, IL10), and chemokines (CXCL10, CCL2) that are correlated with COVID-19 exacerbation." (PMID 35562337, 2022). "Single-cell RNA sequencing (scRNA-seq) shows classical monocytes as the primary source of cytokines and chemokines in severe COVID-19, such as CCL2, CXCL8, IL-6, TNF-α." (PMID 35401519, 2022). "Patients with COVID-19 who died had elevated levels of CCL2/MCP-1 compared to healthy donors, asymptomatic and symptomatic HCWs, and, also, recovered individuals." (PMID 35336861, 2022).
COVID-19 (continued). "Although bile acid synthesis was increased in COVID-19 patients, in CCL2+ T cells and Group 2 macrophages, compared with moderate patients, the metabolic responses related to bile acid synthesis were almost all downregulated in severe patients." (PMID 35350779, 2022). "RNA-seq (RNA-sequencing) from autopsy heart samples and non-COVID-19 donors discovered the significant upregulation of C-C motif chemokine ligand 2 (CCL2), a well-known chemoattractant for migrating macrophages." (PMID 35541905, 2022). "CCL2 is associated with several inflammatory disorders of the lung, including ARDS, the syndrome associated with severe COVID-19, as well as adverse cardiovascular outcomes." (PMID 35749425, 2022). "CXCL10 and CCL2 have been reported as key players in the onset and maintenance of cytokine storm in severe cases of COVID-19." (PMID 36553530, 2022). "The severe COVID-19 group showed significantly higher CCL2 and IL-6 expression levels than the moderate COVID-19 group (P<0.001)." (PMID 35982898, 2022). "CCL2 levels are also increased in bronchoalveolar fluids of severe COVID-19 patients; in these patients there is also an increased recruitment of monocytes into the lungs." (PMID 36559009, 2022). "CCL2 is vital for monocyte recruitment, is expressed at higher levels in lung macrophages of patients with severe COVID-19 and upregulated in response to increases in SARS-CoV-2 viral load levels in infected patients." (PMID 35303909, 2022). "A pathologic hallmark of severe COVID-19 cases is the onset of inflammatory “cytokine storm”, marked by elevated IL1B, TNFA, CCL2, IL6, MIP1A, and IL10 in the plasma." (PMID 35740365, 2022). "For example, the glycolytic pathway was upregulated in CCL2+ T cells (severe vs. moderate patients) and in macrophages and mDCs (COVID-19 patients vs. HCs)." (PMID 35350779, 2022). "We found that fatal COVID-19 was associated with higher levels of IL6, IL10, IL22, CXCL10, CCL2, and CCL20 and lower levels of miR-495-3p, miR-451a, and miR-29b-3p." (PMID 34957382, 2022). "The majority of upregulated cytokines and chemokines, such as IL-6, TNF, CCL2, CCL3, and CXCL10, have been reported to be associated with cytokine release syndrome (CRS), including MAS, in severe COVID-19 cases." (PMID 35440562, 2022). "(2020) have observed that patients hospitalized due to their severe COVID-19 have high levels of CCL2/MCP-1 and CCL3 serum." (PMID 36685603, 2022). "In line with this, enriched CCL2 and CCL7 chemokines in the BAL of COVID-19 patients are linked to the recruitment of CCR + monocytes." (PMID 35284964, 2022). "In cluster 1, IL6, IL1B, TNF, and CCL2 of the top ten key targets were enriched in COVID-19 adverse outcomes pathway, indicating the exacerbation of COVID-19 inflammation on DILI." (PMID 35979235, 2022). "Noteworthily, IL6, IL1B, TNF, and CCL2 in the COVID-19 adverse outcome pathway were found to be the DILI targets, indicating exacerbation of these inflammatory factors of CRS on DILI." (PMID 35979235, 2022). "JUN is a key regulator of inflammatory cytokine genes, such as CCL2, and is expressed at high levels in COVID-19 patients." (PMID 35639708, 2022). "Elevated tissue and circulating levels of cytokines, particularly MCP-1 (CCL2), and reduced numbers of circulating leukocytes relative to neutrophils, correlate with the severity of COVID-19 pathology." (PMID 34863942, 2022). "Of the two plasma and nasopharyngeal cytokines differentially expressed between healthy donors and patients with COVID-19 (IL-10 and CCL2), both were increased during infection in plasma and nasopharyngeal samples." (PMID 34471264, 2021). "The proinflammatory chemokine CCL2 can mediate the directional migration of immune cells and is also higher in COVID-19 patients than in healthy individuals." (PMID 34489974, 2021).
COVID-19 (continued). "These included IL-33, IFN-α2, IFN-λ3, IFN-β and IFN-γ, which were decreased in the nasopharynx of patients with COVID-19, while IL-10 and CCL2 were increased, as compared to healthy controls." (PMID 34471264, 2021). "In summary, BAL of severe COVID-19 patients are enriched with CCL2, the main chemoattractant of inflammatory monocytes, therefore migration of monocytes to the lungs increases, but these monocytes have decreased HLA-DR expression." (PMID 33596401, 2021). "The present study found a marked decrease in PON1 activity and an increase in PON1, CCl2, and galectin-3 concentrations in COVID-19 positive hospitalized patients, compared to healthy individuals." (PMID 34205807, 2021). "They identified neutrophils (IFITM2, IFITM1, H3-H3B, SAT1 and S100A8) and macrophage cluster-1 (CCL8, CCL3, CCL2, KLF6 and SPP1) as the main immune cell subsets associated with severe COVID-19 cases." (PMID 34109284, 2021). "We detected the gene signature for the CXCL10+ CCL2+ inflammatory macrophage state in a higher proportion of macrophages from severe COVID-19 BALF than from other inflamed tissues." (PMID 33879239, 2021). "We demonstrated that the CXCL10+ CCL2+ macrophages from severe COVID-19 lungs share a transcriptional phenotype with macrophages stimulated by TNF-α plus IFN-γ." (PMID 33879239, 2021). "Many cytokines in COVID-19 patients were significantly different from those in healthy individuals, including IL-2, IL-4, IL-6, CCL2, IFN-γ, and TNF-α." (PMID 34489974, 2021). "Systemic cytokine profiles in patients with COVID-19 are similar to those observed in cytokine release syndromes often driven by macrophages, including high levels of circulating IL-6, IL-17, TNFα, CCL2, and CXCL10." (PMID 33643308, 2021). "We observed a CXCL10+ CCL2+ inflammatory macrophage state that is shared and strikingly abundant in severe COVID-19 bronchoalveolar lavage samples, inflamed RA synovium, inflamed CD ileum, and UC colon." (PMID 33879239, 2021). "In both moderate and severe COVID-19 patients, the average concentrations of IL-4, IL-6, IL-10, CCL2, IFN-γ, and TNF-α (P<0.05) were higher than those in healthy donors." (PMID 34489974, 2021). "Most notably, the CXCL10+ CCL2+ inflammatory macrophages predominate in the bronchoalveolar lavage of patients with severe COVID-19, and are also detected in synovial tissue affected by RA and inflamed intestine from patients with IBD." (PMID 33879239, 2021). "Then we detected the expression of CyPA, macrophage marker CD68, CCL2, and IL-6 in lung tissues from 13 cases of COVID-19 patients using multiplex immunofluorescence." (PMID 34564690, 2021). "The described pro-depressive effect of MCP-1/CCL2 and its increased level, especially in severe cases of COVID-19, make it relevant to further research this chemokine in terms of the development of post-COVID depression." (PMID 34575258, 2021). "Taken together, these results indicate that the shared CXCL10+ CCL2+ inflammatory macrophage phenotype is expanded in inflamed tissues and severe COVID-19 BALF." (PMID 33879239, 2021). "These cytokines, such as IL-6, IL-7, CCL-2/MCP-1, CCL-3/CCL-4 MIP-1α/β, TNF-α, and G-CSF, have been implicated in COVID-19 pathogenesis." (PMID 34341347, 2021). "Elevated serum levels of CXCL10 were consistently reported in patients with COVID-19, being positively correlated (together with CCL2) with increased disease severity and, more importantly with an increased risk of mortality." (PMID 33981314, 2021). "For COVID-19, CCL2 recruits neutrophils, monocytes, and macrophages, and CXCL9 and CXCL16 recruit T cells and NK cells to the site of viral infection." (PMID 35002688, 2021). "Patients with MIS-C showed higher plasma levels of C reactive protein (CRP), MPO, IL-6, and of the pro-inflammatory chemokines CXCL8 and CCL2 than COVID-19 children." (PMID 33841438, 2021).
COVID-19 (continued). "The differential expression analysis identified elevated expression of individual inflammatory cytokines and chemokines in the lungs of COVID-19 patients, including CCL2 and IP-10." (PMID 33777047, 2021). "We aimed to investigate the alterations in the circulating levels of PON1, CCL2, and galectin-3 in 126 patients with COVID-19 and their interactions with clinical variables and analytical parameters." (PMID 34205807, 2021). "Considering only the COVID-19 positive patients, we found that those with higher concentrations of IL-10 (>200 ng/L) or IL-6 (>100 ng/L) had higher concentrations of CCL2, galectin-3, and PON1 concentrations." (PMID 34205807, 2021). "Fenofibrate decreases the expression of other cytokines (IL17, CCL2, and CCL20) implicated in COVID-19 pathology." (PMID 34582497, 2021). "In a high-density antibody microarray study of serum proteins from COVID-19 patients, a significant correlation between CCL2 and CXCL10-mediated cytokine signaling pathways has been demonstrated." (PMID 35002688, 2021). "SARS-CoV-2 infection of cardiomyocytes, increased CCL2 expression and macrophage infiltration were reported in their heart tissues, which was confirmed in autopsy samples of COVID-19 patients." (PMID 34531831, 2021). "When COVID-19 progresses to severe illness, an immune system overreaction that culminates in abnormally increased serum levels of CCL2, CCL3, and CXCL10, has been reported." (PMID 33669011, 2021). "Collectively, these findings are consistent with the elevated plasma levels of inflammatory markers observed in COVID-19 patients, where the profile of IL-6, CCL2/MCP-1, and CXCL10/IP-10 are associated with the severity of the disease." (PMID 34572407, 2021). "Higher levels of several inflammatory cytokines including TNF-α, IL-6, and IL-1 and inflammatory chemokines such as CCL2, CCL3, and CXCL10 are associated with disease severity and death in COVID-19 patients." (PMID 33138195, 2020). "Similar to EVALI, patients with COVID-19 showed elevated levels of several cytokines (CCL2/MCP-1, CXCL10/IP-10, CCL3/MIP-1A, and CCL4/MIP1B) in BALF and peripheral blood mononuclear cells." (PMID 32528233, 2020). "Regarding the “HALLMARK_INFLAMMATORY_RESPONSE” gene set, MAFB and MAF were found to oppositely regulate the expression of a cluster of chemokine-encoding genes (CXCL10, CCL2, CCL7, CXCL9) that are associated to the COVID-19 “cytokine storm”." (PMID 33312178, 2020). "Among the identified gene signatures, IFITM2, IFITM1, H3F3B, SAT1, and S100A8 gene signatures were highly associated with neutrophils, while CCL8, CCL3, CCL2, KLF6, and SPP1 were associated with macrophage cluster-1 in severe-COVID-19 patients." (PMID 33138195, 2020). "While the elevation of CXCL10, IL-10, CCL2, IL-6 has been extensively documented in severe COVID-19, our work demonstrates a clear correlation between these cytokines and plasma viral load." (PMID 33317616, 2020). "In COVID-19, men demonstrated lower expression of cytokines with protective effects against viral infection, including CCL2, CCL3, CCL4 and CXCL16, than women." (PMID 32974111, 2020). "Suppressing the CCL2/CCR2 axis may mitigate adverse cardiovascular events in COVID-19 patients by restricting the aggregation of monocytes and macrophages at infection sites." (PMID 40438117, 2025). "A significant increase in plasma CCL2 has been found in COVID-19 patients." (PMID 40584180, 2025). "Additionally, CCL2 positive macrophages have been found to be in excess in bronchoalveolar lavage samples from patients with severe COVID-19." (PMID 40584180, 2025). "CCL2 levels were shown to rise progressively in severe COVID-19 patients with high D-dimer levels." (PMID 40438117, 2025).
COVID-19 (continued). "There is research showing that cytokines closely related to cytokine storms (IL-6, TNF-α) and chemokines such as CXCL10 and CCL2 are significantly elevated in COVID-19 patients with diabetes, indicating that these patients are more prone to excessive inflammatory responses post-infection." (PMID 39654886, 2024). "Nevertheless, the precise mechanism by which family Bifidobacteriaceae and order Bifidobacteriales contribute to the pathogenesis of COVID-19 via CCL2 remains unclear and requires further investigation." (PMID 38803488, 2024). "The complications, severity, and mortality of COVID-19 patients are caused by excessive activation of cytokines (IL-1, IL-6, TNF-a, CCL2, and CXCL10, etc.), namely cytokine storm, which is remarkably similar to the pathogenesis of immune disorders in RA patients." (PMID 38378889, 2024). "Gene expression analyses of CCL2 indicated an upregulation in all COVID-19 patients and significantly different upregulations of CCL2 could be detected in females." (PMID 37832397, 2023). "Significant decreases in plasma concentrations of the pro-inflammatory cytokines IL-6, TNF, and IFN-γ, the leukocyte chemoattractants CXCL8, CXCL10, and CCL2, and the anti-inflammatory cytokines IL-10 and IL-1Ra were observed in COVID-19 patients during dexamethasone treatment." (PMID 37614228, 2023). "In a recent study, it has been reported that depletion of gut microbiota in COVID-19 cohort was linked with increasing concentrations of TNF-α, CXCL10, CCL2 and IL-10 indicating that these taxa might have a role in reducing the ARDS associated cytokine storm." (PMID 37161621, 2023). "Additionally, the expression of genes associated with endothelial dysfunction—namely CCL2, PDGFRA, PDGFB, and PDGFC—was also found to be increased in ACE2-positive brain cells of COVID-19 patients." (PMID 37239234, 2023). "Increased expression of CCL2 during the initial phase of COVID-19 was also reported previously." (PMID 37497545, 2023). "Some mediators that are modulated in bronchoalveolar lavage fluid (BALF) from patients with severe COVID-19 include the chemokines CCL2/3/4/7/8 and C-X-C motif chemokine ligand (CXCL) 1/2/6, as well as the peptide hormone epiregulin (EREG) and members of the ephrin A family (EFNA1 and EFNA5)." (PMID 35281455, 2022). "Hence, symptomatic (mild and severe forms) COVID-19 patients have high levels of CCL-2, together with patients dying from SARS-CoV-2 acute infection." (PMID 36685603, 2022). "We found that most of the metabolic reactions within 11 metabolic pathways are upregulated in CCL2+ T cells and Group 2 macrophages in COVID-19 patients compared with HCs, but metabolic activity is similar in in CCL2+ T cells, Group 2 macrophages, and mDCs in severe and moderate COVID-19 patients." (PMID 35350779, 2022). "Multivariate COX regression analysis revealed that NEAT1 is an independent predictor for survival among COVID-19 patients with an odds ratio of 7.48 and 95% CI (1.03 - 36.08) (P=0.02) while (male sex, smokers, CCL2, TNF-α, and IL-6) were cofactors affecting overall survival." (PMID 35982898, 2022). "Patients who died from COVID-19 stand out for their elevated levels of IL-6, IL-10, and CCL2/MCP-1." (PMID 35336861, 2022). "This assumption is confirmed by the fact that a significant increase of the amount of bacterial lipopolysaccharide (LPS), and soluble sCD14 receptor associated with elevated systemic levels of IL-6, TNF-α, CCL5/RANTES and CCL2/MCP-1 was observed in critically ill patients with COVID-19." (PMID 36325402, 2022). "Moreover, high serum levels of cytokines, such as IL-6, CCL2, CXCL8, CXCL10, IL-2, and IL-10 were associated with COVID-19-related encephalopathy and showed an enhanced systemic inflammatory response." (PMID 36232655, 2022).